GLB1L3 (galactosidase beta 1 like 3)
Description:
Cleaves beta-linked terminal galactosyl residues from gangliosides, glycoproteins, and glycosaminoglycans.
Synonyms: FLJ90231
Tractability: PROTAC: ubiquitination databases record sites on it.
Gene: Protein-coding gene on chromosome 11 (134,274,245 to 134,319,579, forward strand). Ensembl gene ENSG00000166105.
Pathways (Reactome):
Metabolism: CS/DS degradation; Glycosphingolipid catabolism; Keratan sulfate degradation
Gene Ontology:
Molecular function: beta-galactosidase activity; hydrolase activity, hydrolyzing O-glycosyl compounds
Biological process: galactose catabolic process; carbohydrate metabolic process
Cellular component: vacuole
Genetic constraint (gnomAD): Loss-of-function variants: 61 observed, 58.23 expected, observed/expected ratio (o/e) 1.05, 90% interval 0.85 to 1.3. The upper end of that interval is the gene's LOEUF score, 1.3, which puts it in group 5 of 6, group 1 being the genes least tolerant of losing a copy. Missense variants: 696 observed, 675.36 expected, observed/expected ratio (o/e) 1.03, 90% interval 0.97 to 1.1. Synonymous variants: 268 observed, 258.46 expected, observed/expected ratio (o/e) 1.04, 90% interval 0.94 to 1.15.
Homologues: Orthologues: chimpanzee GLB1L3 (99% identical), macaque GLB1L3 (93% identical), pig GLB1L3 (73% identical), mouse Glb1l3 (66% identical), rat Glb1l3 (65% identical), guinea pig GLB1L3 (65% identical), tropical clawed frog glb1l2 (47% identical), zebrafish si:dkey-224e22.2 (46% identical), Caenorhabditis elegans bgal-1 (31% identical), Drosophila melanogaster Ect3 (31% identical), Drosophila melanogaster Gal (30% identical), Caenorhabditis elegans bgal-2 (26% identical), and 1 more. Paralogues in human: GLB1L2 (56% identical), GLB1 (32% identical), GLB1L (32% identical).
Diseases named in the same sentence as GLB1L3 in open-access papers:
GLB1L3 is named in the same sentence as 8 diseases in open-access papers, as found by Europe PMC text mining. Sharing a sentence is not in itself a finding about the gene and the disease. The quoted sentences say what the papers report.
schizophrenia (2 papers, 2021 to 2025). A major psychotic disorder characterized by abnormalities in the perception or expression of reality. "GLB1L3, expressed predominantly in the central nervous system, is involved in carbohydrate metabolism and beta-galactosidase activity, and has been implicated in schizophrenia." (PMID 40124684, 2025). "Combining the cross-tissue summary metric results, we identified 3 genes passing the FDR threshold for both schizophrenia and ALS, namely ZNHIT3, GLB1L3 and TMEM194A." (PMID 35004692, 2021).
retinal degeneration (1 paper, 2011). Degeneration of the retina. "Altered expression started in the differentiating retina and persisted during aging, indicating that the early downregulation of Glb1l3 is mostly due to the absence of 11-cis retinal rather than to the progression of retinal degeneration." (PMID 21633714, 2011).
retinal disease (1 paper, 2021). "Another downregulated gene associated with retinal disease is Glb1l3 (Galactosidase beta 1 like 3), which has been implicated in age-related metabolic stress and found to be reduced in Rpe65 knockout mice, connecting it to the pathophysiology of Leber congenital amaurosis." (PMID 34404875, 2021).
cancer (2 papers, 2011 to 2025). A tumor composed of atypical neoplastic, often pleomorphic cells that invade other tissues. "In relation to GLB1L3, there is very limited information about its function and its expression in cancer; however, the expression levels of this gene were found to be significantly increased in invasive lung adenocarcinoma (LUAD) compared to normal tissues." (PMID 40508156, 2025).
GLB1L3 also shares sentences with these, for which no sentence is quoted: Leber congenital amaurosis (2 papers); prediabetes (2); cervical cancer (1); Obesity (1).